KAT2B (lysine acetyltransferase 2B)
Description:
Functions as a histone acetyltransferase (HAT) to promote transcriptional activation. Has significant histone acetyltransferase activity with core histones (H3 and H4), and also with nucleosome core particles. Has a a strong preference for acetylation of H3 at 'Lys-9' (H3K9ac). Also acetylates non-histone proteins, such as ACLY, MAPRE1/EB1, PLK4, RRP9/U3-55K and TBX5. Inhibits cell-cycle progression and counteracts the mitogenic activity of the adenoviral oncoprotein E1A. Acts as a circadian transcriptional coactivator which enhances the activity of the circadian transcriptional activators: NPAS2-BMAL1 and CLOCK-BMAL1 heterodimers. Involved in heart and limb development by mediating acetylation of TBX5, acetylation regulating nucleocytoplasmic shuttling of TBX5. Acts as a negative regulator of centrosome amplification by mediating acetylation of PLK4. Acetylates RRP9/U3-55K, a core subunit of the U3 snoRNP complex, impairing pre-rRNA processing. Acetylates MAPRE1/EB1, promoting dynamic kinetochore-microtubule interactions in early mitosis. Also acetylates spermidine. (Microbial infection) In case of HIV-1 infection, it is recruited by the viral protein Tat. Regulates Tat's transactivating activity and may help inducing chromatin remodeling of proviral genes.
Synonyms: P/CAF; PCAF; GCN5; GCN5L; CAF
Tractability: Small molecule: a structure with a bound ligand is known; a high-quality ligand is known; it has a high-quality binding pocket; it belongs to a druggable protein family. PROTAC: it is named in the literature on targeted protein degradation; ubiquitination databases record sites on it; a small molecule that binds it is known.
Target class: Writer; Histone acetyltransferase; GNAT family; Epigenetic regulator
Chemical probes: GSK4027 (high quality), L-Moses (high quality), L-Moses
Safety:
Unwanted effects reported when the protein is acted on. In parentheses: how it was acted on, where the effect was seen, and who reports it.
drug dependence (source: ClinPGx)
Gene: Protein-coding gene on chromosome 3 (20,040,400 to 20,154,404, forward strand). Ensembl gene ENSG00000114166.
Subcellular location: Nucleus; Cytoplasm, cytoskeleton, microtubule organizing center, centrosome; Cytoplasm
Subcellular location (Human Protein Atlas): Nucleoplasm; Cytosol
Pathways (Reactome):
Gene expression (Transcription): B-WICH complex positively regulates rRNA expression; Formation of WDR5-containing histone-modifying complexes; Notch-HLH transcription pathway; RNA Polymerase I Transcription Initiation; RUNX1 regulates genes involved in megakaryocyte differentiation and platelet function; RUNX3 regulates NOTCH signaling; Regulation of FOXO transcriptional activity by acetylation; YAP1- and WWTR1 (TAZ)-stimulated gene expression
Signal Transduction: Estrogen-dependent gene expression; NOTCH1 Intracellular Domain Regulates Transcription; NOTCH3 Intracellular Domain Regulates Transcription; NOTCH4 Intracellular Domain Regulates Transcription; Pre-NOTCH Transcription and Translation
Developmental Biology: Differentiation of naive CD4+ T cells to T helper 2 cells (Th2 cells); Formation of paraxial mesoderm; Regulation of gene expression in late stage (branching morphogenesis) pancreatic bud precursor cells
Disease: Constitutive Signaling by NOTCH1 HD+PEST Domain Mutants; Constitutive Signaling by NOTCH1 PEST Domain Mutants
Chromatin organization: HATs acetylate histones
Metabolism of proteins: Metalloprotease DUBs
Muscle contraction: Physiological factors
Gene Ontology:
Molecular function: acetyltransferase activity; DNA-binding transcription factor binding; enzyme activator activity; histone acetyltransferase activity; histone deacetylase binding; histone H3K9 acetyltransferase activity; L-lysine N-acetyltransferase activity, acting on acetyl phosphate as donor; protein binding; protein-lysine-acetyltransferase activity; transcription coactivator activity; transcription coregulator activity; chromatin binding; cyclin-dependent protein serine/threonine kinase inhibitor activity; protein kinase binding; acyltransferase activity, transferring groups other than amino-acyl groups; diamine N-acetyltransferase activity; histone acetyltransferase binding; RNA polymerase II transcription regulatory region sequence-specific DNA binding
Biological process: cellular response to insulin stimulus; chromatin remodeling; internal peptidyl-lysine acetylation; negative regulation of cell population proliferation; negative regulation of centriole replication; negative regulation of ferroptosis; negative regulation of rRNA processing; negative regulation of transcription by RNA polymerase II; negative regulation of ubiquitin-dependent protein catabolic process; positive regulation of attachment of mitotic spindle microtubules to kinetochore; positive regulation of fatty acid biosynthetic process; positive regulation of transcription by RNA polymerase II; protein acetylation; heart development; limb development; positive regulation of DNA-templated transcription; regulation of cell cycle; regulation of DNA repair; regulation of DNA-templated transcription; regulation of embryonic development; regulation of RNA splicing; transcription initiation-coupled chromatin remodeling; cellular response to oxidative stress; cellular response to parathyroid hormone stimulus; memory; and 4 more
Cellular component: ATAC complex; centrosome; cytoplasm; cytosol; nucleoplasm; nucleus; protein-containing complex; mitotic spindle; SAGA complex; A band; actomyosin; chromatin; histone acetyltransferase complex; I band; kinetochore
Genetic constraint (gnomAD): Loss-of-function variants: 22 observed, 68.13 expected, observed/expected ratio (o/e) 0.32, 90% interval 0.23 to 0.46. The upper end of that interval is the gene's LOEUF score, 0.46, which puts it in group 2 of 6, group 1 being the genes least tolerant of losing a copy. Missense variants: 574 observed, 701.78 expected, observed/expected ratio (o/e) 0.82, 90% interval 0.76 to 0.88. Synonymous variants: 286 observed, 268.35 expected, observed/expected ratio (o/e) 1.07, 90% interval 0.97 to 1.17.
Homologues: Orthologues: chimpanzee KAT2B (99% identical), macaque KAT2B (99% identical), dog KAT2B (98% identical), pig KAT2B (97% identical), mouse Kat2b (91% identical), rat Kat2b (91% identical), rabbit KAT2B (85% identical), tropical clawed frog kat2b (82% identical), zebrafish kat2b (77% identical), Caenorhabditis elegans baz-2 (13% identical), Drosophila melanogaster Acf (11% identical). Paralogues in human: KAT2A (70% identical), BPTF (29% identical), BAZ2B (16% identical), BAZ2A (14% identical), BAZ1B (12% identical), BAZ1A (10% identical), BRD2 (9% identical), BRD4 (9% identical), BRD3 (9% identical), CECR2 (9% identical), BRDT (8% identical).
Diseases named in the same sentence as KAT2B in open-access papers:
KAT2B is named in the same sentence as 130 diseases in open-access papers, as found by Europe PMC text mining. Sharing a sentence is not in itself a finding about the gene and the disease. The quoted sentences say what the papers report.
hepatocellular carcinoma (24 papers, 2011 to 2025). A malignant tumor that arises from hepatocytes. "Downregulation of KAT2B has been reported in several cancers and is associated with poor prognosis, including hepatocellular carcinoma, esophageal squamous cell carcinomas, lung adenocarcinoma, gastric cancer, colorectal cancer and cervical carcinoma." (PMID 38641672, 2024). "Previous studies showed KAT2B expression to be downregulated in esophageal squamous cell and hepatocellular carcinomas, and in the latter case, to be associated with inferior overall survival." (PMID 36750554, 2023). "KAT2B was downregulated in hepatocellular carcinoma tissues and significantly associated with a favorable prognosis for patients." (PMID 36814797, 2023). "In lung cancer these include the lysine acetyltransferases KAT13D (Clock), KAT5 (Tip60), KAT2B (PCAF) and KAT13B (SRC-3), while SIRT-1 expression has been linked to cisplatin resistance in epidermoid and hepatoma cells." (PMID 24212667, 2011). "In this context, a previous study shows that KAT2B plays a tumor suppressive role in hepatocellular carcinoma (HCC) via regulating GLI1/BCL2 signaling pathway." (PMID 38641672, 2024). "In hepatocellular carcinoma (HCC), studies have disclosed a tumor-suppressive role of KAT2B by inhibiting the growth/metastasis and accelerating the apoptosis of HCC cells." (PMID 38641672, 2024). "Additionally*** ***, KAT2B is also capable of acetylating histone H4, inhibiting AKT signal as well as regulating GLI1/Bcl-2/Bax axis to induce apoptosis, thereby inhibiting occurrence and hepatocellular carcinoma development." (PMID 34130593, 2021).
breast carcinoma (22 papers, 2006 to 2025). "Elevated expression of NELF-E and KAT2B is associated with poorer prognosis in breast cancer patients, highlighting the clinical relevance of our findings." (PMID 37117180, 2023). "The tumor suppressor role of the histone acetyltransferase, KAT2B (also known as PCAF or p300/CBP-associated factor) was previously proposed in breast cancer, esophageal squamous cell cancer, and gastric carcinoma." (PMID 30020984, 2018). "Importantly, we also validated that loss of KAT2B led to impaired breast cancer stemness in a different metastatic breast cancer cell line, BT-549." (PMID 37117180, 2023). "Inactivation of KAT2B was associated with downregulation of the EMT pathway, whereas elevated expression of KAT2B was correlated with reduced survival in breast cancer patients." (PMID 40229280, 2025). "Taken together, our data reveal mechanistic insights into how KAT2B drives breast cancer metastasis and contributes to SLUG-mediated gene activation in association with NELF." (PMID 37117180, 2023). "Here the authors show that transcriptional complex NELF interacts with SLUG, and co-opts KAT2B, to promote the expression of epithelial-mesenchymal transition (EMT) and stemness-associated genes in breast cancer." (PMID 37117180, 2023). "We therefore decided to focus on KAT2B and determine how it contributes to breast cancer progression." (PMID 37117180, 2023). "Researches have shown that KAT2B is concerned about occurrence and development of gastric cancer, colorectal cancer, breast cancer, lung cancer, liver cancer as well as other tumors." (PMID 34130593, 2021). "Histone H4K8 acetylation by KAT2B, a GNAT family HAT, reduced replication fork stability in breast cancer cells in vitro, and reduced levels of KAT2B may predict PARP inhibitor resistance." (PMID 40165290, 2025). "Furthermore, higher protein expression of KAT2B also correlated with a poorer survival outcome of breast cancer patients." (PMID 37117180, 2023). "Notably, genetic and pharmacological inactivation of KAT2B results in impaired EMT and loss of stemness properties, similar to NELF-E ablation, thereby establishing the functional importance of the NELF-E-KAT2B regulatory axis in breast cancer carcinogenesis." (PMID 37117180, 2023). "GSEA of TCGA cohorts revealed a significant high correlation between KAT2B and CIITA RNA expression levels in breast cancer." (PMID 40495188, 2025). "KAT2B, EP300, KAT6A (MYST family), and KAT2A (GNAT family) are recruited to ER-responsive promoters and are critical for estrogen-dependent proliferation of ER-positive breast cancer cells." (PMID 40165290, 2025). "Specifically, we showed that NELF activates the EMT and mammary stem cell transcriptional programs in breast cancer, and defined an epigenetic mechanism by which NELF co-opts the EMT TF, SLUG, and histone acetyltransferase, KAT2B, to coordinate gene expression reprogramming during EMT." (PMID 37117180, 2023). "The apparent non-essentiality of KAT2B and NELF for normal development, together with their acquired dependency in aggressive breast cancer, highlight the exciting prospect of developing therapeutic candidates to target NELF-E-KAT2B in cancer." (PMID 37117180, 2023).
gastric cancer (14 papers, 2014 to 2025). A primary or metastatic malignant neoplasm involving the stomach. "KAT2B is able to inhibit tumorigenicity in gastric cancer cells not only in vivo but in vitro, prevent gastric cancer cells from entering S phase from G1 stage and its decrease in expression linked with poor clinical prognosis of intestinal gastric cancer." (PMID 34130593, 2021). "KAT2B is a histone lysine acetyltransferase that regulates gene transcription via interaction with p300/CREB-binding protein; down-regulation of KAT2B promotes intestinal-type gastric cancer progression and is correlated with a poor clinical outcome." (PMID 28603669, 2017). "Moreover, KAT2B suppressed the tumorigenicity of gastric cancer in vitro and in vivo and was correlated with aggressive clinical features." (PMID 36814797, 2023).
lung carcinoma (11 papers, 2011 to 2025). "In response to high glucose levels, ACLY is acetylated at K540, K546, and K554 by lysine acetyltransferase (KAT2B), reducing the binding between ACLY and the RING-type E3 ubiquitin ligase UBR4, thereby promoting lung cancer progression." (PMID 39944823, 2025).
glioblastoma (8 papers, 2007 to 2026). The most malignant astrocytic tumor (WHO grade IV). "Down-regulation of KAT2B in medulloblastoma and glioblastoma cells brings on decline in proliferation together with rise in apoptosis." (PMID 34130593, 2021). "KAT2B is also a proven oncogene that activates gene transcription in medulloblastoma and glioblastoma." (PMID 33330099, 2020). "Regarding the first signature network component, hsa-mir-137, hsa-mir-330, hsa-mir-149, hsa-mir-107, hsa-mir-181b were among the miRNAs whose experimentally validated targets (such as CTBP1, CDC42, CDK6, E2F1, VEGFA, AKT1, KAT2B) affect the pathways which play a crucial role in glioblastoma biology." (PMID 28045122, 2017). "KAT2B-mediated AKT1acetylation is able to enhance phosphorylation with AKT1 at threonine and serine sites, and further promotes glioblastoma cells proliferation." (PMID 34130593, 2021).
prostate carcinoma (8 papers, 2015 to 2025). A carcinoma that arises from epithelial cells of the prostate gland. "In vitro KAT assays confirmed that salicylate directly inhibited PCAF/Kat2b, Tip60/Kat5 and hMOF/Kat8, and this inhibition was likely involved in the reversal of EMT in the metastatic prostate cancer cell line PC-3." (PMID 28717171, 2017).
cervical carcinoma (7 papers, 2015 to 2024). A carcinoma arising from either the exocervical squamous epithelium or the endocervical glandular epithelium. "KAT2B signally down-regulated in cervical cancer tissues, and low-expression KAT2B closely linked with poor prognosis in patients." (PMID 34130593, 2021). "Similarly, KAT2B was significantly downregulated in cervical cancer tissues, and its low expression was closely associated with a poor prognosis." (PMID 36814797, 2023). "Conversely, KAT2B plays an oncogenic role in multiple types of cancer, such as gastric, liver, and cervical cancers." (PMID 36814797, 2023). "After transfecting miR-93-5p mimics or inhibitors, we observed that KAT2B expression in cervical cancer cells was inhibited by miR-93-5p overexpression." (PMID 34130593, 2021). "Our findings indicated that low KAT2B expression was also involved in EMT process of cervical cancer cells, revealing how dysregulated miR-93-5p expression acted in EMT process of tumor cells." (PMID 34130593, 2021). "This research intends to exploit expression, clinical significance as well as how KAT2B functions in cervical cancer." (PMID 34130593, 2021). "Subsequently, using qPCR and Western, we detected KAT2B mRNA and protein expression in normal cervical squamous cell line H8 and cervical cancer cell lines C33A, HeLa, SiHa, as well as CaSki, respectively." (PMID 34130593, 2021). "With aim to probe into how KAT2B functions in regulating proliferation, migration together with invasion of cervical cancer, we successfully conducted a cell model with low and over KAT2B expression." (PMID 34130593, 2021). "The results suggested that, in comparison with normal cervical squamous epithelial cells H8, KAT2B mRNA and protein expression in 4 cervical cancer cell lines were all diminished." (PMID 34130593, 2021). "we observed equal phenomenon in KAT2B and miR-93-5p expression in cervical carcinoma samples via qPCR." (PMID 34130593, 2021). "Consistent with clinicopathological analysis, we found that KAT2B knockdown in cervical cancer cells made for proliferation and migration enhancement, while KAT2B overexpression functioned in inhibition." (PMID 34130593, 2021). "We further verified how KAT2B functioned in cervical cancer cells and confirmed that KAT2B worked in inhibiting cervical cancer." (PMID 34130593, 2021). "Similar to TCGA data, qPCR results implied that in contrast to adjacent normal tissues, KAT2B mRNA expression was signally diminished in cervical cancer tissues." (PMID 34130593, 2021). "Since KAT2B expression and function in cervical carcinoma have not been found, our research aims to probe into the expression, clinical significance as well as function of KAT2B in cervical cancer tissue." (PMID 34130593, 2021). "In terms of the obtained results, the hub proteins KAT2B, PARP1, CDK1, GSK3B, WNK1, and CRYAB have been associated with several cancers in previous studies, but their association with cervical cancer is proposed here for the first time." (PMID 30020984, 2018). "We showed that the down regulation of KAT2B and PCNA expression was associated with a higher risk of cervical cancer." (PMID 30020984, 2018). "Inhibiting KAT2B could promote proliferation together with metastasis of cervical cancer cell line C33A, while KAT2B overexpression was capable of inhibiting proliferation as well as metastasis of cervical cancer cell line CaSki." (PMID 34130593, 2021). "Since miRNAs acts pivotally in regulating gene expression, it is of great significance to determine whether KAT2B expression is under regulation by specific miRNAs in cervical cancer." (PMID 34130593, 2021). "Additionally, we adopted qPCR to determine KAT2B mRNA expression in cervical cancer and matched adjacent tissues." (PMID 34130593, 2021). "With aim to initially exploit whether KAT2B act essentially in cervical cancer progression, we first applied immunohistochemistry to detect KAT2B expression in clinical samples." (PMID 34130593, 2021).
cervical carcinoma (continued). "In our research, we confirmed for the first time that KAT2B could inhibit cervical cancer progression." (PMID 34130593, 2021). "Furthermore, the interaction of KAT2B with HPV16 E7, which is a cervical cancer associated oncoprotein, was also reported." (PMID 30020984, 2018). "Interestingly, knocking down KAT2B could increase N-cadherin together with Vimentin expression in cervical cancer cells but decrease ZO-1 expression." (PMID 34130593, 2021). "Therefore, KAT2B may also affect proliferation and metastasis of cervical cancer cells via similar mechanism." (PMID 34130593, 2021). "In cervical cancer tissues, KAT2B protein expression was strongly positive for 17.31% (9/52), weakly positive for 11.54% (6/52), negative for 71.15% (37/52), suggesting that KAT2B protein expression in cervical cancer tissues was signally down-regulated." (PMID 34130593, 2021). "Furthermore, the KAT2B, PARP1, CDK1, GSK3B, WNK1, and CRYAB, proteins are associated with various cancer types, but their roles in cervical cancer have not been identified." (PMID 30020984, 2018). "Underlying mechanism was that low-expression KAT2B inhibited migration and invasion of cervical carcinoma by inhibiting EMT, and KAT2B expression was under negative regulation by miR-93-5p." (PMID 34130593, 2021).